MC1R (melanocortin 1 receptor)
Diseases named in the same sentence as MC1R in open-access papers (continued):
Sharing a sentence is not in itself a finding about the gene and the disease.
basal cell carcinoma (4 papers, 2016 to 2024). A carcinoma involving the basal cells. "We tested the associations for 19 previously reported basal cell carcinoma-related SNPs (candidate gene association analysis), and found that rs1805007 (MC1R locus) was significantly associated with risk of mKCs (p-value = 2.80x10-4)." (PMID 28081215, 2017).
colon carcinoma (4 papers, 2002 to 2025). "The macrophage/monocyte line THP-1 showed the same levels of α-MSH binding as LPS- or cytokine stimulated monocytes, confirming the MC1R expression in this line, while an ovarian and a colon carcinoma (OV3507, SW480) included as controls only bound low to insignificant levels of α-MSH." (PMID 12177778, 2002). "We developed and validated a five-immune gene model of colon cancer, including LBP, TFR2, UCN, UTS2, and MC1R." (PMID 32375704, 2020).
colorectal cancer (4 papers, 2020 to 2025). A primary or metastatic malignant neoplasm that affects the colon or rectum. "Fourth, MC1R SNPs were also associated with the development of colorectal cancer; for example, the rs2228479 locus genotype was correlated with Ki67 status, and the rs885479 locus genotype was correlated with age and T stage." (PMID 34698109, 2021). "Secondly, there is a lack of further in vivo and in vitro experiments for functional verification, especially the exploration of the specific role and mechanism of MC1R gene in colorectal cancer (CRC) is still insufficient." (PMID 40547309, 2025). "MC1R plays a pivotal role in the progression of colorectal cancer and may serve as a marker of worse prognosis in colorectal cancer." (PMID 35872794, 2022). "A few studies have reported a relationship between MC1R and colorectal cancer (CRC)." (PMID 34698109, 2021). "Therefore, we speculate that one of the ways that MC1R participates in the development of colorectal cancer is by regulating the proliferation of tumor cells." (PMID 34698109, 2021).
psoriasis (4 papers, 2012 to 2025). An autoimmune condition characterized by red, well-delineated plaques with silvery scales that are usually on the extensor surfaces and scalp. "To conclude, this study showed the associations between MC1R and DCT polymorphisms and psoriasis in the Tatar population, suggesting that these genetic variants may contribute to a predisposition to psoriasis." (PMID 40650250, 2025). "Mutation experiments of the MC-1R gene showed that the induction of DCreg was mediated by the binding of α-MSH to the MC-1R and that this effect could ameliorate psoriasis in vitro as well as in vivo." (PMID 22969767, 2012).
systemic sclerosis (4 papers, 2022 to 2025). A chronic disorder, possibly autoimmune, marked by excessive production of collagen which results in hardening and thickening of body tissues. "Among them, α-MSH analogs play a role in atopic dermatitis and scleroderma, and MC1R agonist Dersimelagon has shown effectiveness in systemic sclerosis." (PMID 41002740, 2025). "Ongoing investigations suggest that drugs targeting MC1R may hold promise in treating patients with high-need conditions such as systemic sclerosis, neuroinflammation, rheumatoid arthritis, fibrosis, and others." (PMID 37569558, 2023). "The purpose of this study is to investigate the potential of dersimelagon, a novel oral MC1R agonist, as a therapeutic agent for systemic sclerosis (SSc)." (PMID 36050717, 2022).
atopic dermatitis (3 papers, 2020 to 2025). "In an atopic dermatitis murine model, the expression of α-MSH was mainly observed in keratinocytes, and scratching responses in these mice were attenuated by an antagonist of melanocortin 1 receptor (MC1R), which is one of the receptors of α-MSH." (PMID 33182442, 2020).
brain injury (3 papers, 2021 to 2022). Acute and chronic (see also brain INJURIES, CHRONIC) injuries to the brain, including the cerebral hemispheres, CEREBELLUM, and brain STEM. "MC1R activation also exerted anti-inflammatory, antiapoptotic, and neuroprotective effects in a mice model of experimental traumatic brain injury." (PMID 35140838, 2022). "However, whether MC1R activation can attenuate oxidative stress and neuronal apoptosis after hypoxic-ischemic- (HI-) induced brain injury remains unknown." (PMID 35140838, 2022). "In conclusion, activation of MC1R with BMS-470539 downregulated pro-inflammatory cytokines, promoted microglial M2 polarization, reduced peripheral immune cell infiltration, and improved neurological deficits after neonatal HI brain injury in rats." (PMID 33468172, 2021). "Therefore, the present study is aimed at exploring whether the selective MC1R agonist, BMS-470539, could attenuate oxidative stress and neuronal apoptosis via MC1R/cAMP/PKA/Nurr1 signaling pathway after neonatal hypoxic-ischemic brain injury in rats." (PMID 35140838, 2022).
Fanconi anemia (3 papers, 2022 to 2024). Fanconi anemia (FA) is a hereditary DNA repair disorder characterized by progressive pancytopenia with bone marrow failure, variable congenital malformations and predisposition to develop hematological or solid tumors. "MC1R gene is involved in the neuroactive ligand-receptor interaction and melanogenesis pathways while the FANCA gene was observed in the Fanconi anemia pathway." (PMID 35747604, 2022).
Hypercholesterolemia (3 papers, 2021 to 2025). An increased concentration of cholesterol in the blood. "We here show that the loss of MC1-R signaling in hepatocytes causes hypercholesterolemia and enhanced lipid accumulation in the liver, and disturbs bile acid metabolism." (PMID 37490042, 2023). "In conclusion, the present results demonstrate that MC1-R signaling in hepatocytes regulates cholesterol and bile acid metabolism and its deficiency leads to hypercholesterolemia and enhanced lipid accumulation and fibrosis in the liver." (PMID 37490042, 2023). "In any case, these data uncover a functional role for MC1-R signaling in hepatic cholesterol metabolism that might be of therapeutic relevance in the management of hypercholesterolemia." (PMID 37490042, 2023). "MC1R-knockout mice exhibit significant hepatomegaly, accompanied by elevated hepatic and plasma cholesterol and triglyceride levels, suggesting that hepatocyte MC1R signaling regulates cholesterol and bile acid metabolism, while its absence promotes hypercholesterolemia." (PMID 40547309, 2025). "Conversely, MC1-R activation in hepatocytes reduced cellular cholesterol content and increased LDL and HDL uptake, which are preventive mechanisms against hypercholesterolemia and the progression of NAFLD." (PMID 37490042, 2023). "However, in the present study, hematopoietic MC1-R deficiency caused monocytosis and enhanced HSC proliferation in the absence of exaggerated hypercholesterolemia." (PMID 34868038, 2021).
keratinocyte carcinoma (3 papers, 2023 to 2024). A skin cancer arising from the keratin-producing cells of the epidermis. "Most of these genes are pigmentation-related genes (i.e., SLC45A2, TYR, OCA2, MC1R, and ASIP) and have a biological importance of lighter pigmentation in susceptibility to keratinocyte carcinoma." (PMID 38182794, 2024). "Using whole exome sequencing data, we performed groupwise tests for rare missense variants in our dataset and found robust associations (p < 10−6, Burden Zeggini test) between MC1R, EPHA8, EPO, MYCT1, ADGRG3, and MGME1 and keratinocyte cancer." (PMID 37444464, 2023).
major depressive disorder (3 papers, 2013 to 2025). An episode of depression lasting two or more weeks without an intervening episode of mania. "Collaborative involvement of the MC1R, MC2R, and MC5R genes are implicated in the risk of major depressive disorder." (PMID 41002740, 2025). "Although both, MSTN and MC1R, are surrounded by significant SNPs it is obvious that they seem to lie in a sXPEHH depression compared to a little more distant SNPs." (PMID 24359457, 2013). "Meanwhile, MC1R, MC2R, and MC5R genes are involved in the risk of major depressive disorder." (PMID 41002740, 2025). "The recent literature shows that three genes (MC1R, MC2R, and MC5R) increase the risk of major depressive disorder (MDD), and one gene (MC4R) is associated with an increased risk of type 2 diabetes, but its association needs to be researched further." (PMID 41002740, 2025). "Three melanocortin receptor genes (MC1R, MC2R, and MC5R) contribute to the risk of major depressive disorder (MDD), and one melanocortin receptor gene (MC4R) contributes to the risk of type 2 diabetes (T2D)." (PMID 35955479, 2022).
nephrotic syndrome (3 papers, 2016 to 2023). A collection of symptoms that include severe edema, proteinuria, and hypoalbuminemia; it is indicative of renal dysfunction. "Increased glomerular expression of one of the MCRs, the MC1R, was found to be linked to nephrotic syndrome, both in patients and in the PAN rat." (PMID 30356069, 2018). "Four patients with congenital red hair color and nephrotic syndrome caused by idiopathic membranous nephropathy or focal segmental glomerulosclerosis were confirmed by gene sequencing to bear dominant-negative MC1R mutations." (PMID 27270328, 2016). "In agreement with our findings, no clinical evidence exists so far supporting any associations between RHC or genetic variations of MC1R and the susceptibility to nephrotic syndrome, proteinuria or glomerulopathies." (PMID 27270328, 2016). "In summary, this study proposes MC1R as being responsible for the beneficial effects of ACTH on the glomerular filtration barrier in patients with nephrotic syndrome." (PMID 30356069, 2018). "We show that MC1R is the ACTH receptor being augmented in nephrotic syndrome, thereby promoting restoration of stressfibers in podocytes by inhibition of EGFR signaling." (PMID 30356069, 2018). "The melanocortin-1 receptor (MC1R) in podocytes has been suggested as the mediator of the ACTH renoprotective effect in patients with nephrotic syndrome with the mechanism of action beeing stabilization of the podocyte actin cytoskeleton." (PMID 30356069, 2018). "We found that glomerular MC1R expression was increased in nephrotic syndrome, both in humans and in a rat model." (PMID 30356069, 2018). "In this study, we investigate MC1R regulation in patients and rats with nephrotic syndrome in combination with an unbiased approach to identify MC1R signaling pathways using phosphoproteomics." (PMID 30356069, 2018). "In summary, ACTH therapy successfully induced remission of proteinuria in MC1R mutant red-haired patients with steroid resistant nephrotic syndrome." (PMID 27270328, 2016). "The fact that MC1R was found to be the most abundant ACTH receptor in the glomeruli, in combination with it being the only MCR that is augmented in nephrotic syndrome, confirm its role as being the receptor responsible for the beneficial effects of ACTH seen in patients with nephrotic syndrome." (PMID 30356069, 2018).
oculocutaneous albinism type 2 (3 papers, 2018 to 2022). Oculocutaneous albinism type 2 (OCA2) is a type of OCA and the most common form of OCA seen in the African population, characterized by variable hypopigmentation of the skin and hair, numerous characteristic ocular changes and misrouting of the optic nerves at the chiasm. "However, besides oculocutaneous albinism type 2 in humans, associations of MC1R variants with white coat colour are rare." (PMID 33213385, 2020).
Adrenal insufficiency (2 papers, 2020 to 2021). Insufficient production of steroid hormones (primarily cortisol) by the adrenal glands. "Despite this residual MC1R stimulation, these patients still have adrenal insufficiency since they lack ACTH which is the only ligand for MC2R that is present only in the adrenal cortex." (PMID 34177811, 2021). "Several studies have examined the role of MC1R in adrenal insufficiency." (PMID 32483162, 2020).
Alzheimer disease (2 papers, 2024 to 2025). A progressive, neurodegenerative disease characterized by loss of function and death of nerve cells in several areas of the brain leading to loss of cognitive function such as memory and language. "MC1R gene variants are also associated with the risk of Alzheimer’s disease." (PMID 41002740, 2025).
basal cell carcinoma of skin (2 papers, 2012 to 2022). "MC1R variants were associated with susceptibility to basal cell carcinoma of skin and there is an interaction with host factors and the XRCC3 gene." (PMID 22759494, 2012).
cardiac hypertrophy (2 papers, 2024 to 2025). "Cardiomyocyte‐specific MC1R deficiency attenuates physiological and pathological cardiac hypertrophy in mice, while pharmacological activation of MC1R promotes cardiomyocyte hypertrophy." (PMID 39921516, 2025). "Taken together, these findings demonstrate that MC1R deficiency in cardiomyocytes blunts pathological cardiac hypertrophy but leads to compromised systolic and diastolic function." (PMID 39921516, 2025). "In addition to affecting pathological cardiac remodeling, global and cardiomyocyte‐specific MC1R deficiency attenuated physiological cardiac hypertrophy and improvement in EF in response to 5‐week voluntary wheel running." (PMID 39921516, 2025). "Indeed, cardiomyocyte‐specific deletion of MC1R caused a similar phenotype with attenuated cardiac hypertrophy in response to pathological stimuli and endurance training." (PMID 39921516, 2025). "To test this hypothesis, we used Mc1re/e mice, as a model of global MC1R deficiency and subjected them to models of pathological and physiological cardiac hypertrophy." (PMID 39921516, 2025). "Recessive yellow mice, as a model of global MC1R deficiency, and cardiomyocyte‐specific MC1R knockout mice were subjected to transverse aortic constriction or voluntary wheel running to induce pathological or physiological cardiac hypertrophy, respectively." (PMID 39921516, 2025). "First, we demonstrated that MC1R is abundantly present in the mouse heart and that its expression gradually declines during the progression of pathological cardiac hypertrophy." (PMID 39921516, 2025). "These phenotypic traits were recapitulated in TAC‐operated Mc1r‐cKO mice, indicating that MC1R signaling, specifically in cardiomyocytes, regulates pathological cardiac hypertrophy." (PMID 39921516, 2025). "Following the previously discovered expression of MC1R in the heart, we first found that the expression of MC1R in the mouse heart declines during the development of pathological cardiac hypertrophy." (PMID 39921516, 2025). "Global or cardiomyocyte‐specific silencing of MC1R signaling attenuated exercise‐ and pressure overload–induced cardiac hypertrophy but led concomitantly to LV dilatation and to subtle changes in LV systolic and diastolic function." (PMID 39921516, 2025). "Cumulative and average daily running distance was similar between control Myh6‐MCM and Mc1r‐cKO mice, indicating equal stimulus for physiological cardiac hypertrophy." (PMID 39921516, 2025). "We observed that MC1R is expressed in the mouse heart and downregulated in response to pathological cardiac hypertrophy." (PMID 39921516, 2025). "For instance, MC1R regulates brain injury by modulating mitochondrial metabolism through this pathway, while acacetin alleviates cardiac hypertrophy via AMPK/SIRT1/PGC‐1α." (PMID 39325807, 2024). "We next explored whether the expression of MC1R in the heart is modulated during the development of pathological cardiac hypertrophy." (PMID 39921516, 2025). "Collectively, the lack of exercise‐induced cardiac hypertrophy and improvement in EF indicate that MC1R deficiency is not beneficial for physiological cardiac remodeling." (PMID 39921516, 2025). "Mc1re/e mice displayed features of attenuated cardiac hypertrophy, which led us to engineer a cardiomyocyte‐specific MC1R knockout mouse model to investigate whether the observed phenotype was dependent on dysfunctional MC1R signaling in cardiomyocytes." (PMID 39921516, 2025). "A similar phenotype was observed in angiotensin II–infused Mc1r‐cKO, demonstrating that blunting of pathological cardiac hypertrophy appears independent of the chosen model." (PMID 39921516, 2025). "Next, we aimed to test whether the phenotype of Mc1r‐cKO mice is independent of the chosen model of pathological cardiac hypertrophy." (PMID 39921516, 2025).
Cerebral ischemia (2 papers, 2021 to 2025). Restriction of arterial blood supply to the brain associated with insufficient oxygenation to support the metabolic requirements of the tissue. "Previous studies showed that the activation of MC1R significantly attenuated brain injury by reducing neuroinflammation in SAH, ICH, and cerebral ischemia-reperfusion (I/R) injury." (PMID 33468172, 2021).
chondrosarcoma (2 papers, 2018). A malignant cartilaginous matrix-producing mesenchymal neoplasm arising from the bone and soft tissue. "The detection of MC1R in human articular chondrocytes is in accordance with the observation that also a human chondrosarcoma cell line, likewise expresses functional MC1R." (PMID 29373492, 2018). "A chondrosarcoma cell line also expresses MC1R and reduces levels of post‐inflammatory MMP13 transcription in response to αMSH, while healthy primary chondrocytes do not." (PMID 29316344, 2018).
diabetic retinopathy (2 papers, 2024). "MC1R and MC5R agonists reduced anti-inflammatory cytokines and chemokines and enhanced manganese superoxide dismutase and glutathione peroxidase levels of retinal cells, indicating that MC1R and MC5R agonists exert a protective role on experimental diabetic retinopathy." (PMID 38397406, 2024).
dyslipidemia (2 papers, 2023 to 2024). "In a separate experiment, mice were fed a Western diet for 12 weeks to investigate whether hepatocyte-specific MC1-R deficiency exacerbates diet-induced dyslipidemia." (PMID 37490042, 2023).
endothelial dysfunction (2 papers, 2014 to 2025). In vascular diseases, endothelial dysfunction is a systemic pathological state of the endothelium (the inner lining of blood vessels) and can be broadly defined as an imbalance between vasodilating and vasoconstricting substances produced by (or acting on) the endothelium. "A synthetic MC1R agonist (BMS-470539), for instance, was demonstrated to inhibit leucocyte trafficking in the inflamed vasculature, and the natural agonist α-melanocyte-stimulating hormone was shown to regulate vascular NO availability and to protect against endothelial dysfunction." (PMID 24967348, 2014). "For example, Mc1re/e mice have endothelial dysfunction and increased arterial stiffness and pulse pressure due to nonfunctional MC1R in endothelial cells, which could increase cardiac afterload and explain why sham‐operated Mc1re/e mice showed increased Nppb expression." (PMID 39921516, 2025).
fibrosis (2 papers, 2022 to 2025). the formation of excess fibrous connective tissue in an organ or tissue in a reparative or reactive process. "However, there were no signs of exaggerated cardiac fibrosis in Mc1r‐cKO mice, which could explain the functional consequences of MC1R deficiency." (PMID 39921516, 2025).